DNAJB3P (DnaJ heat shock protein family (Hsp40) member B3, pseudogene)
Description:
May operate as a co-chaperone of the male germ cell- and haploid stage-specific Hsp70 proteins.
Synonyms: HCG3; formerly DNAJB3
Gene: Transcribed unitary pseudogene on chromosome 2 (233,743,188 to 233,743,916, reverse strand). Ensembl gene ENSG00000227802.